THBS4 (thrombospondin 4)
Diseases named in the same sentence as THBS4 in open-access papers (continued):
Sharing a sentence is not in itself a finding about the gene and the disease.
muscular dystrophy (7 papers, 2014 to 2024). Muscular dystrophy (MD) refers to a group of more than 30 genetic diseases characterized by progressive weakness and degeneration of the skeletal muscles that control movement. "Thrombospondin-4 is an extracellular protein involved in extracellular matrix assembly, and if mutated gives rise to muscular dystrophy, similar to other structural proteins such as dystrophin and collagen." (PMID 39627572, 2024). "It would therefore be logical to assume that loss of Thbs4 in Sgcb mice would lead to an exacerbation of muscular dystrophy in the same way as was seen in Sgcd model." (PMID 38926599, 2024). "Here we show that Thrombospondin-4 (Thbs4) regulates skeletal muscle integrity and its susceptibility to muscular dystrophy through organization of membrane attachment complexes." (PMID 27669143, 2016). "This worsened the muscle wasting in the mutant mice, and furthermore, deleting the gene for thrombospondin-4 also caused otherwise normal mice to develop muscular dystrophy in their old age." (PMID 27669143, 2016). "Hence, it has been proposed that Thbs4 is an attractive therapeutic target for muscular dystrophies involving mutations in the DGC43." (PMID 38926599, 2024). "Here we aimed at verifying whether Thbs4 could influence the phenotype of other muscular dystrophies associated with the DGC." (PMID 38926599, 2024). "Hence, it has been interpreted that loss of Thbs4 predisposes to muscular dystrophy." (PMID 38926599, 2024). "Analysis of human muscle biopsies from patients with muscular dystrophy found enriched THBS4 expression, consistent with dystrophic mouse models." (PMID 38175727, 2024). "It has previously been shown that at one year of age, Thbs4 KO mice exhibit increased histopathological signs of muscular dystrophy, as well as reduced physical capacity." (PMID 38926599, 2024). "Loss of the Thbs4 gene causes spontaneous dystrophic changes with aging and accelerates disease in 2 mouse models of muscular dystrophy, while overexpression of mouse Thbs4 is protective and mitigates dystrophic disease." (PMID 27669143, 2016). "In agreement, muscle-specific overexpression of Drosophila Tsp or mouse Thbs4 rescues a Drosophila model of muscular dystrophy with augmented membrane residence of βPS integrin." (PMID 27669143, 2016). "When myofibers in mammals become injured, as is the case during muscular dystrophy, they produce more proteins called thrombospondins – with thrombospondin-4 being the most common." (PMID 27669143, 2016). "This functional conservation emphasizes the fundamental importance of Thbs’ as regulators of cellular attachment and membrane stability and identifies Thbs4 as a potential therapeutic target for muscular dystrophy." (PMID 27669143, 2016). "Thrombospondin-4 has emerged to be a promising therapy target for both limb-girdle muscular dystrophy type 2F and Duchenne muscular dystrophy, as its overexpression mitigated dystrophic phenotype in mouse models of these muscular dystrophies." (PMID 38926599, 2024). "Hence, thrombospondin-4 has been considered a candidate molecule for therapy of muscular dystrophies involving the DGC." (PMID 38926599, 2024). "This further suggests that Thbs4 does not have an intracellular role in promoting receptor trafficking to the sarcolemma in laminin α2-deficient muscular dystrophy." (PMID 38926599, 2024). "In this study, we aimed to verify whether Thbs4 is a universal target for DGC-related muscular dystrophies." (PMID 38926599, 2024). "It has therefore been proposed that Thbs4 could be a therapeutic agent for all muscular dystrophies involving adhesion complexes in the sarcolemma." (PMID 38926599, 2024). "We examined older mice to explore whether β-sarcoglycan-deficient mice lacking Thbs4 would exhibit worsening of muscular dystrophy with age compared to Sgcb KO mice." (PMID 38926599, 2024).
muscular dystrophy (continued). "However, just as in Sgcb mice, Thbs4 was found only in the extracellular compartment in laminin α2-deficient muscle, and we did not observed exacerbation of muscular dystrophy by deletion of Thbs4." (PMID 38926599, 2024). "The reduction in THBS4 and TGF-β proteins in MRL ECM corresponds to the decreased collagen accumulation and is consistent with markedly delayed progression of the muscular dystrophy process." (PMID 38175727, 2024). "Thrombospondin-4 (THBS4), a multifunctional glycoprotein that modifies muscular dystrophy outcome, was also markedly downregulated in the Sgcg-MRL myoscaffolds but was abundant in the Sgcg-D2 dECM." (PMID 38175727, 2024). "Thbs4 was upregulated in dy3K/dy3K and Sgcb KO muscle, but only in the extracellular compartment and not intracellularly as described for other muscular dystrophy mouse models." (PMID 38926599, 2024). "Moreover, we did not observe a difference between Sgcb KO and Sgcb/Thbs4 mice regarding histopathological signs of muscular dystrophy." (PMID 38926599, 2024). "Nevertheless, we suggest that Thbs4 might not necessarily be a universal therapeutic target for muscular dystrophies involving the DGC." (PMID 38926599, 2024). "Thbs4 KO muscle did not exhibit any signs of muscular dystrophy in the examined muscles." (PMID 38926599, 2024). "Our results suggest that thrombospondin-4 might not be a relevant therapeutic target for all muscular dystrophies involving the DGC." (PMID 38926599, 2024). "The deletion of the Thbs4 gene did not result in an exacerbation of muscular dystrophy in any of these two disorders, indicating that Thbs4 does not have the same disease-modifying effect as has been shown in mice models of Duchenne muscular dystrophy and LGMD2F." (PMID 38926599, 2024).
cardiomyopathy (6 papers, 2017 to 2025). A disease of the heart muscle or myocardium proper. "Defective flux of Thrombospondin 4 through the secretory pathway impairs the stability of the cardiomyocyte membrane and leads to cardiomyopathy." (PMID 40709343, 2025). "Analysis of pathways that were dysregulated across cardiomyopathy phenotypes identified shared genes that were associated with extracellular matrix remodeling and thus likely fibrosis (THY1, CILP, OGN, THBS4, ASPN, HAPLN1,and SMOC2), as well as calcium (ADIPOQ, ASPN, THBS4, STAT4, and SMOC2)." (PMID 28098235, 2017). "This indicates that absence of Thbs4 does not cause acceleration of cardiomyopathy in Sgcb KO mice." (PMID 38926599, 2024). "Based on the findings of cell type-specific regulatory activity, the most active TFs in each of the 4 cardiomyopathy fibroblast subpopulations, including NR3C1 (C0 THBS4+ Fibroblasts), KLF4 (C1 LINC01133+ Fibroblasts), FOSB (C2 FGF7+ Fibroblasts), FOS (C3 AGT + Fibroblasts)." (PMID 38799173, 2024).
gallbladder cancer (6 papers, 2021 to 2025). "Another study in gallbladder cancer found that THBS4 is secreted by a variety of cells, but its main source is also CAF; in addition to CAF, the abundance of tumor-associated macrophages can also be regulated by THBS4 and play a role in tumor invasiveness." (PMID 40303998, 2025). "In gallbladder cancer cells, integrin α2 on the surface is activated by thrombospondin 4 (TSP4) secreted from CAFs." (PMID 37153737, 2023). "Moreover, thrombospondin 4 (TSP-4) secreted from CAFs binds to integrin α2 to promote HSF1 phosphorylation at Ser326 to support the malignant phenotypes of gallbladder cancer cells, including cell proliferation, epithelial-mesenchymal transition (EMT) and cancer stemness." (PMID 39261452, 2024).
colon cancer (5 papers, 2020 to 2025). "In contrast, in colon cancer, the THBS4 gene is methylated and silenced, while increased expression of THBS4 in colon cancer colonies significantly inhibits tumor growth." (PMID 40303998, 2025). "We found increased levels of THBS4 and PDGFRb in tumor tissues compared to normal tissues of colon cancer patients." (PMID 32899998, 2020). "Correlation analyses using TCGA data showed that THBS2 is significantly positively correlated with THBS1, THBS3, THBS4, and THBS5 in colon cancer." (PMID 34804159, 2021). "Furthermore, the spatial co-localization of CAFs marker genes with THBS2, THBS4, and COMP in colon cancer supports these findings." (PMID 38827236, 2024). "Therefore, to investigate the effects of TGFβ on PDGFRβ and THBS4 overexpression in CRC, we examined the mRNA levels of PDGFRβ and THBS4 after treatment with TGFβ for 12 h in DLD-1 cells, which is a colon cancer cell line." (PMID 32899998, 2020).
diabetes (5 papers, 2020 to 2026). "SHBG and PRSS2 might explain the beneficial association with IHD; testosterone, SHBG, CCL5, CNDP1, F11, LCN2, and THBS4 might explain the association with diabetes, which provides insights for drug development." (PMID 41882153, 2026). "Thrombospondin-4 (TSP4) has been shown previously to cause peripheral arterial disease in diabetes." (PMID 36902363, 2023). "Our results revealed that THBS4 reshapes the immune microenvironment by interfering with the immune infiltration of DC cells and macrophages, and ultimately regulates the progression of diabetes and COPD." (PMID 39845878, 2024). "While the molecular mechanisms of THBS4 in diabetes and COPD still require further clarification, intervening in THBS1 may be an effective therapeutic strategy." (PMID 39845878, 2024). "In addition, thrombospondin-4 (TSP-4) levels were significantly increased with PAD severity in patients with concomitant diabetes and could be a novel marker of atherosclerotic activity." (PMID 33222686, 2020). "Multiple machine learning algorithms identified 4 shared biomarkers for COPD and diabetes, including CADPS, EDNRB, THBS4 and TMEM27." (PMID 39845878, 2024). "Ultimately, we conducted a cross-analysis of the 4 potential biomarkers gene sets and 4 genes as shared biomarkers for COPD and diabetes, including CADPS, EDNRB, THBS4 and TMEM27." (PMID 39845878, 2024). "Based on microarray data of multi-center COPD and diabetes patients, the gene expression analysis results showed that CADPS and TMEM27 were significantly upregulated in both COPD and diabetes, while EDNR8 and THBS4 were significantly downregulated." (PMID 39845878, 2024). "While this study provides compelling evidence for the role of CADPS, EDNRB, THBS4, and TMEM27 as shared biomarkers between COPD and diabetes, it is important to acknowledge that the specific molecular mechanisms underlying their involvement in disease progression remain incompletely understood." (PMID 39845878, 2024). "In this study, we integrated microarray data from multiple cohorts of COPD and diabetes patients, and comprehensively utilized various machine learning algorithms to identify shared biomarkers in COPD and diabetes patients, including CADPS, EDNRB, THBS4 and TMEM27." (PMID 39845878, 2024). "Although the molecular mechanisms of THBS4 in diabetes and COPD have not been fully elucidated, it has been identified as a potential risk factor for diabetes in existing reports, which may be related to its regulation of the immune microenvironment." (PMID 39845878, 2024).
atherosclerosis (4 papers, 2019 to 2022). A disease characterized by the build-up of fatty material and calcium deposition in the arterial wall resulting in partial or complete occlusion of the arterial lumen. "Thbs4 supported local vascular inflammation in the atherosclerosis model and was associated with inflammation." (PMID 35327480, 2022).
Hypertension (4 papers, 2015 to 2025). The presence of chronic increased pressure in the systemic arterial system. "The most prominent of these, Thbs4, is related to vascular ER stress that is associated with hypertension." (PMID 26356734, 2015). "Regarding Ala387Pro variants of the THBS4 gene, there was a higher prevalence of hypertension for GG + GC compared to CC carriers (95.8% vs. 4.2%, p = 0.016) and a lower prevalence of depression for CC + GC carriers compared with to GG carriers (31.9% vs. 68.1%, p = 0.019)." (PMID 30972713, 2019). "Co-IF revealed strong ANTXR1 and THBS4 colocalization within the expanding CF population following hypertension, recapitulating the pattern observed post-MI." (PMID 41039173, 2025). "Further analysis of the expression of THBS4, the cleaved form of ATF6α, and two of its targets by western blot confirmed the up-regulation of this pathway at the protein level in hypertension." (PMID 26356734, 2015).
Obesity (4 papers, 2020 to 2025). Accumulation of substantial excess body fat. "Other biomarkers that have previously been linked to obesity were also found to be increased, including THBS4, which mediates cell communication and meteorin-like." (PMID 40806703, 2025). "Other members of the EC matrix—thrombospondins—such as those identified in our study (THBS2, THBS3, and THBS4), are mainly detected in visceral adipose tissues and their increased expression level is associated with obesity." (PMID 32485856, 2020). "This analysis showed that some proteins, such as COL1A1, COL6A3, FABP4, LEP, LGALS1, and THBS4, are obesity-specific, and GDF15, LPL, MCFD2, REG1A, REG1B, and TCN2 are T2D-specific." (PMID 38732002, 2024).
osteoarthritis (4 papers, 2015 to 2025). A noninflammatory degenerative joint disease occurring chiefly in older persons, characterized by degeneration of the articular cartilage, hypertrophy of bone at the margins and changes in the synovial membrane. "Finally, in an attempt to obtain a molecular explanation for the transient phenotype of Thbs4-deficient mice, we monitored expression of known osteoarthritis susceptibility (OAS) genes in articular cartilage from 26 weeks old mice." (PMID 26629997, 2015). "We therefore measured THBS4 serum concentrations in individuals with mono-osteoarthritis or poly-osteoarthritis using a commercially available ELISA against intact THBS4." (PMID 26629997, 2015). "For example, searching for THBS4 reveals human osteoarthritis datasets where THBS4 is also up-regulated illustrating how SkeletalVis allows rapid cross-species comparison of newly available gene expression responses against this existing repository of knowledge." (PMID 30481257, 2019). "The absence of evidence supporting a function of THBS4 as a signaling molecule essentially rules out the possibility that the development of drugs activating THBS4 is a possible approach for the treatment of osteoarthritis." (PMID 26629997, 2015).
peripheral nerve injuries (4 papers, 2016 to 2025). "Peripheral nerve injury is also associated with up-regulation of expression of thrombospondin-4 (TSP4) in spinal cord and DRG of the spinal cord." (PMID 27610084, 2016). "Our study provides a detailed investigation of the mechanisms by which Thbs4 functions in peripheral nerve injury repair both in vivo and in vitro, offering new insights and potential directions for the repair of peripheral nerve injuries." (PMID 41153662, 2025).
Cognitive impairment (3 papers, 2017 to 2025). Abnormal cognition is characterized by deficits in thinking, reasoning, or remembering. "THBS4 and Talin-1 were also both validated using ELISA as being significantly upregulated in the TBI patients with cognitive impairment." (PMID 28251161, 2017).
colon adenocarcinoma (3 papers, 2021 to 2024). "THBS1, THBS2 and THBS5 proteins exhibited relatively high expression in six cancer types compared to normal samples, except for THBS5 in clear cell renal cell carcinoma (CCRCC), while THBS3 and THBS4 proteins showed lower levels in colon adenocarcinoma (COAD) and HNSC." (PMID 39732719, 2024). "THBS2, THBS3, THBS4, and THBS5 were differentially expressed in TGCT (testicular germ cell tumors) and COAD (colon adenocarcinoma)." (PMID 34804159, 2021).
fibrosis (3 papers, 2019 to 2025). the formation of excess fibrous connective tissue in an organ or tissue in a reparative or reactive process. "Among them, AEBP1 has been demonstrated to be associated with fibrosis in DCM and THBS4 has also been demonstrated to promote skin fibrosis." (PMID 38185631, 2024).
gastric adenocarcinoma (3 papers, 2021 to 2025). "A typical example is gastric adenocarcinoma where, in contrast to PTMC, THBS4 is derived from tumor-associated fibroblasts in diffuse gastric adenocarcinoma, whereas THBS4 expression is not detectable in tumor cells." (PMID 40303998, 2025). "THBS4 was identified as a diffuse-type gastric adenocarcinoma marker, and described to promote GC cell proliferation and metastasis." (PMID 35768842, 2022). "THBS4 was located in the tumor stroma in gastric adenocarcinoma." (PMID 34390328, 2021).
ischemia (3 papers, 2019 to 2025). A hypoperfusion of the BLOOD through an organ or tissue caused by a PATHOLOGIC CONSTRICTION or obstruction of its BLOOD VESSELS, or an absence of BLOOD CIRCULATION. "To identify the proportion of NSCs that differentiated into Thbs4-positive astrocytes following ischemia, we analyzed the co-expression of Thbs4 with tdTOM after MCAO." (PMID 40827993, 2025).
ischemic stroke (3 papers, 2017 to 2024). A stroke disorder caused by obstruction of blood flow to the brain, due to thrombotic (local blood clot formation) or embolic (due to a blood clot or other material traveling from another site) event. "Furthermore, complement C3a treatment stimulated overall white matter reorganization, upregulating the expression of THBS4 in the peri-infarct cortex of ischemic stroke, thereby promoting inflammatory responses and tissue repair." (PMID 39845878, 2024). "On the other hand, SVZ-derived astrocytes have a crucial role in ischemic stroke: photothrombotic cortical ischemia induces a strong gliogenic, Notch1-dependent response in the SVZ, which generates thrombospondin-4 (Thbs4)-positive astrocytes." (PMID 28553634, 2017).
liver cancer (3 papers, 2020 to 2024). An epithelial or non-epithelial malignant neoplasm that arises from the liver. "Overexpression of THBS4 promotes the proliferation and migration of liver cancer cells, participates in the regulation of epithelial-mesenchymal transition progression and interacts with members of the integrin family to modulate the FAK/PI3K/AKT pathway." (PMID 39010084, 2024). "THBS4 as a target is very promising for the treatment of advanced liver cancer." (PMID 32068233, 2020).
peripheral arterial disease (3 papers, 2020 to 2023). A disorder of the arteries supplying the upper and lower extremity and the visceral organs. "THBS4 has been associated with more advanced peripheral artery disease and T2D." (PMID 37679740, 2023).
peritonitis (3 papers, 2020 to 2024). Inflammation of the peritoneum (tissue that lines the abdominal wall and covers most of the organs in the abdomen). "To evaluate the expression and the effect of TSP-4 on macrophages in a model of acute inflammation, we induced peritonitis in WT, Thbs4−/−, and P387-TSP-4-KI mice by IP injection of LPS." (PMID 31974349, 2020). "Expression of CD68, a marker of macrophages, was upregulated in peritoneal tissues of WT and even more dramatically in Thbs4−/− mice with LPS-induced peritonitis." (PMID 31974349, 2020). "Furthermore, THBS4 produced by pro-inflammatory mouse macrophages supports their accumulation and inflammatory activity in an autocrine manner in an LPS-induced peritonitis model suggesting an immunomodulatory role for THBS4 in inflammation and potentially in wound healing." (PMID 34631719, 2021). "Surprisingly, TSP-4 deletion in the Thbs4−/− mice did not reduce the number of macrophages recovered in a saline lavage (free macrophages) compared with WT mice, but we collected fewer macrophages from the cavity of P387-TSP-4-KI mice than from WT mice after LPS-induced peritonitis." (PMID 31974349, 2020).
tendinopathy (3 papers, 2020 to 2022). "Overexpression of MAPK1 significantly increased collagen type 1 and Thbs4 levels and decreased the number of cells in the wound region of tendinopathy rats." (PMID 35635083, 2022). "Consistent with our data, miR-148a-3p was reported to promote the expression of thrombospondin-4 to enhance endothelial cell angiogenesis in tendinopathy." (PMID 33117083, 2020).